COL12A1 (collagen type XII alpha 1 chain)
Diseases named in the same sentence as COL12A1 in open-access papers (continued):
Sharing a sentence is not in itself a finding about the gene and the disease.
pancreatic cancer (continued). "The result indicated COL12A1 might be a diagnosis and prognosis biomarker in pancreatic cancer." (PMID 36900272, 2023). "The established pseudogenes/lncRNAs-hsa-miR-26b-5p-COL12A1 ceRNA sub-network may help us to comprehensively understand the pathogenesis of PDAC and provide promising diagnostic biomarkers or effective therapeutic targets for pancreatic cancer." (PMID 33027767, 2020). "Hence, the hsa-miR-26b-5p-COL12A1 axis may be a potential pathway in regulating the progression of pancreatic cancer." (PMID 33027767, 2020). "Oncomine analysis of cancer vs. normal tissue confirmed that COL12A1, FN1, ITGA2, LAMB3, LAMC2, THBS2, and VCAN were significantly overexpressed in pancreatic cancer from different datasets." (PMID 34007003, 2021). "Based on the ceRNA hypothesis, a novel HCG11/NAMPTP1-miR-26b-5p-COL12A1 triple sub-network was constructed, which showed that overexpressed lncRNAs/pseudogenes mediate downregulation of hsa-miR-26b-5p leading to increased expression of COL12A1 in the progression of pancreatic cancer." (PMID 33027767, 2020). "Moreover, in the Pei pancreas dataset, COL12A1, FN1, ITGA2, LAMB3, LAMC2, THBS2, and VCAN mRNA expression levels were higher in pancreatic cancer tissue than in normal pancreatic tissue samples." (PMID 34007003, 2021). "The three genes, COL12A1 APOL1 and MMP14, may be vital in mediating the progression of pancreatic cancer." (PMID 33027767, 2020). "Although the upregulation of COL12A1 and COL5A2 has not been experimentally shown in pancreatic cancer, their abnormal overexpression has been experimentally shown in other cancer types." (PMID 34094925, 2021).
colon cancer (7 papers, 2015 to 2023). "High COL12A1 expression has been correlated with poor survival and cancer metastasis in gastric cancer and colon cancer." (PMID 36900272, 2023). "Interestingly, Col12a1 was previously connected to metastasis in breast and colon cancer." (PMID 31505876, 2019). "Among the upregulated stromal cell-enriched proteins, some proteins have been reported to be potential markers in colon cancer prognosis or tumorigenicity, such as collagen XII (COL12A1), thrombospondin 2 (THBS2), collagen triple helix repeat-containing protein 1 (CTHRC1) and COL5A2." (PMID 26338966, 2015).
myopathic EDS (7 papers, 2019 to 2025). "It has recently been associated with variants of the COL12A1 gene, which are referred to as myopathic Ehlers-Danlos syndrome (mEDS; OMIM 616470), Ullrich congenital muscular dystrophy-2 (UCMD2), and Bethlem myopathy-2 (BTHLM2; 616471)." (PMID 40508193, 2025). "Myopathic EDS—Biallelic and heterozygous defects in the COL12A1 gene, encoding the pro-α1-chains of type XII collagen, cause the rare myopathic EDS (mEDS)." (PMID 35205310, 2022). "Mutations in COL12A1 cause myopathic EDS (mEDS), the symptoms of which overlap with those of spEDS." (PMID 40857410, 2025). "It has been associated with variants of the COL12A1 gene, which are known as Ullrich congenital muscular dystrophy-2 (UCMD2; 616470) and Bethlem myopathy-2 (BTHLM2; 616471)." (PMID 40508193, 2025). "This study aims to detail, in the two families, the mainly myopathic and functional aspects and to critically but constructively review the literature regarding the cases of myopathic Ehlers-Danlos syndrome (mEDS) related to COL12A1." (PMID 40508193, 2025). "COL12A1‐RD, emerges as a clinical overlap syndrome involving muscle and connective tissue, alternatively also classified as myopathic EDS." (PMID 39923201, 2025).
Bethlem myopathy (5 papers, 2019 to 2025). A usually autosomal dominant inherited movement disorder caused by mutations in the COL6A1, COL6A2, and COL6A3 genes. "Specific COL12A1 genotypes were also previously linked to Bethlem myopathy (BM)." (PMID 34062975, 2021). "Even though phenotypic overlap between patients with COL12A1‐related myopathy and patients with Bethlem myopathy, a form of COL6‐related dystrophy due to mutations in collagen VI genes (COL6A1, COL6A2, or COL6A3) has been noted, several features help distinguish these disorders." (PMID 31509352, 2019). "COL6‐RD encompasses a spectrum of disease ranging from the severe Ullrich congenital muscular dystrophy, to intermediate and Bethlem myopathy on the milder end, and is therefore a relevant consideration in the differential diagnosis of the COL12A1‐RD spectrum." (PMID 39923201, 2025). "In the CM group, we identified the COL12A1 variant c.5894G>A and the COL6A1 variant c.850G>A, which have been previously reported in patients with Bethlem myopathy or Ullrich congenital muscular dystrophy." (PMID 38818036, 2024). "However, the current OMIM classification for COL12A1 that includes Ullrich congenital muscular dystrophy 2 and Bethlem myopathy (OMIM: 120320) should be reconsidered as there are distinct phenotypic differences." (PMID 39923201, 2025).
gastric tumor (4 papers, 2010 to 2023). "Consistently, JYQHD inhibited gastric tumor growth, while oe-COL12A1 attenuated the anti-tumor effect of JYQHD and increased tumor volume and weight compared with JYQHD group." (PMID 37700383, 2023).
ovarian cancer (4 papers, 2020 to 2025). A primary or metastatic malignant neoplasm involving the ovary. "In agreement with our findings, another study found that high COL12A1 expression in ovarian cancer was associated with reduced OS." (PMID 40565351, 2025). "Increased COL12A1 expression has also been reported in ovarian cancer A2780 cisplatin-resistant (23.9-fold change increased) and A2780 doxorubicin-resistant cell lines (16.4-fold change increased) compared to parental A2780 cells." (PMID 40565351, 2025). "Together these studies suggest a relationship between COL12A1 and ovarian cancer chemotherapy resistance but warrants further investigation." (PMID 40565351, 2025). "However, using proteomics, COL12A1 was identified as one of the down-regulated proteins in cisplatin-resistant ovarian cancer cell lines." (PMID 40565351, 2025). "It was found that COL12A1 expression was abnormally elevated in ovarian cancer (OC), and overexpression of COL12A1 could also induce drug resistance in OC cell lines." (PMID 35879877, 2023). "COL12A1 expression was predicted to be significantly upregulated in cancers such as colorectal, breast, pancreatic, and ovary cancer, which suggested that COL12A1 might be an oncogene in these cancers." (PMID 32356618, 2020). "We also report for the first time that the suppression of TIMP-2 in ovarian cancer cell lines is associated with a loss of E-Cad mRNA expression with a corresponding increase in the mRNA expression of N-Cad, VIM and a decrease in the mRNA expression of COL12A1." (PMID 33023532, 2020). "We validated the expression of proteins of interest (COL12A1, FUBP1, PLEC, SLC4A1, and TKT) using immunohistochemistry (IHC) and further characterized their expression in online ovarian cancer databases." (PMID 40565351, 2025).
pancreatic adenocarcinoma (4 papers, 2022 to 2025). "Overexpression of COL12A1 was significantly correlated with poor prognosis in pancreatic adenocarcinoma patients." (PMID 35407556, 2022).
Ullrich congenital muscular dystrophy (4 papers, 2023 to 2025). Ullrich congenital muscular dystrophy (UCMD) is characterized by early-onset, generalized and slowly progressive muscle weakness, multiple proximal joint contractures, marked hypermobility of the distal joints and normal intelligence. "By contrast, Stickler syndrome has the most collagens (six) linked to this syndrome (COL2A1, COL9A1, COL9A2, COL9A3, COL11A1, and COL11A2), followed by Ullrich congenital muscular dystrophy, with four collagens associated (COL6A1, COL6A2, COL6A3, and COL12A1)." (PMID 37189830, 2023).
liver fibrosis (3 papers, 2019 to 2025). "Among these, Col12a1 (Collagen Type XII Alpha 1 Chain) associated with cancer which is elevated in liver fibrosis, Plag1 (Pleomorphic adenoma gene 1) an oncogene associated with hepatoblastoma and age-related decrease in skeletal muscle." (PMID 35511946, 2022). "Most of the pro-fibrotic genes were associated with the “Hepatic fibrosis/hepatic stellate cell activation” pathway, with the exception of COL12A1 and EDN-1, the latter being among the top upregulated genes." (PMID 31969876, 2019).
Obesity (3 papers, 2017 to 2025). Accumulation of substantial excess body fat. "In contrast, the adipogenesis genes COL12A1, FBN1 and RBP4, as well as the genes CASP6 and DPT that involved in inflammation or immune response, were downregulated in obese pigs but upregulated in obese human, consistent with previous reports showing their upregulation in obesity." (PMID 40658709, 2025).
pancreatic ductal adenocarcinoma (3 papers, 2020 to 2024). An infiltrating adenocarcinoma that arises from the epithelial cells of the pancreas. "It is noteworthy that COL12A1 expression has been linked specifically to myofibroblast CAFs (myoCAFs) in pancreatic ductal adenocarcinoma (PDAC) and correlated with poor survival." (PMID 39048763, 2024).
adenoma (2 papers, 2018 to 2019). A neoplasm arising from the epithelium. "Moreover, expression of COL12A1 was reported to clearly distinguish between normal, adenoma, and carcinoma group and may have further diagnostic potential." (PMID 30175151, 2018).
breast tumors (2 papers, 2022 to 2024). "Our analysis identified a strong positive correlation between COL12A1 expression and CAF score, further reinforcing CAFs as the major source of COL12A1 in breast tumours." (PMID 35933466, 2022). "To investigate the relationship between COL12A1 and CAF presence in human tumours we assigned a CAF score to each breast tumour dataset from the TCGA cohort using the CAF marker genes identified in human scRNA-seq data from breast tumours above." (PMID 35933466, 2022).
cardiac hypertrophy (2 papers, 2020 to 2022). "COL12A1 and THBS1 are genes that, when elevated, can promote fibrosis and cause cardiac remodeling, a hallmark of cardiac hypertrophy." (PMID 32878883, 2020). "Our results suggested that Col12a1 may play a key part in the process of cardiac hypertrophy through a ceRNA regulatory network." (PMID 35211156, 2022). "Our findings suggest that three mRNAs (Col12a1, Thbs1, and Tgfbr3), four miRNAs (miR-20a-5p, miR-27b-3p, miR-342-3p, and miR-378a-3p), and four related circRNAs (circ_0002702, circ_0110609, circ_0013751, and circ_0047959) may play a key role in cardiac hypertrophy." (PMID 35211156, 2022).
intrahepatic cholangiocarcinoma (2 papers, 2023). A carcinoma that arises from the intrahepatic bile duct epithelium in any site of the intrahepatic biliary tree. "Nevertheless, the expression pattern and the function of COL12A1 in intrahepatic cholangiocarcinoma (iCCA) remain unknown." (PMID 36694230, 2023).
keratoconus (2 papers, 2022 to 2023). A degenerative, structural disorder of the eye, characterized by a cone-shaped protrusion of the cornea. "And some of their target genes, such as FN1, COL12A1, TIMP3 and FBLN5, were associated with ECM and also down-regulated in keratoconus." (PMID 35821117, 2022). "A recent study utilized whole exome sequencing (WES) to identify 34 keratoconus-related genes and noted genetic variation for several genes that are pertinent to EDS, including COL5A1, TNXB, ZNF469, and COL12A1." (PMID 37374145, 2023).
muscular dystrophies (2 papers, 2022 to 2025). "Diseases related to collagen VI and XII exhibit muscle biopsy characteristics that differ from those of muscular dystrophy; therefore, it is appropriate to collect the varied forms under the umbrella of related myopathy (RM), that is, COL6-RM and COL12A1-RM, respectively." (PMID 40508193, 2025).
osteosarcoma (2 papers, 2021 to 2023). A usually aggressive malignant bone-forming mesenchymal neoplasm, predominantly affecting adolescents and young adults. "TNC, LUM, COL12A1, COL6A3, and BGN are among the DEPs that differentiate the chondroblastic group from other subtypes of osteosarcoma." (PMID 37681913, 2023).
scrapie (2 papers, 2011 to 2014). A fatal disease of the nervous system in sheep and goats, characterized by pruritus, debility, and locomotor incoordination. "In our results, three types of collagen (COL1A2, COL3A1 and COL12A1) exhibited downregulation in sheep with natural scrapie and might be related to the loss of their neuroprotective role." (PMID 21629698, 2011). "We and others have previously reported altered expression of COL1A2, COL3A1 and COL12A1 and other ECM related genes in the CNS of sheep infected with scrapie and other prion diseases and in leukocyte-depleted splenic cells from scrapie-infected mice." (PMID 24450868, 2014).
Anxiety (1 paper, 2019). Intense feelings of nervousness, tension, or panic often arise in response to interpersonal stresses. "The 6q13q14.1 deletion of ~ 10 Mb affects 33 genes including the candidate drivers PHIP and COL12A1, which have been associated with developmental delay, anxiety, and facial dysmorphisms in other patients." (PMID 31801603, 2019).
aortic stenosis (1 paper, 2022). Aortic valve stenosis is a aortic valve disease caused by the incomplete opening of the aortic valve. "Noteworthy, among these genes, immunoglobulin κ constant (IGKC) and IGKV1-12 are involved in antigenic responses, AXIN2 plays a well-known role in vascular calcification, and COL12A1 has been implicated in aortic stenosis and osteo-chondrogenic differentiation." (PMID 36437309, 2022).
B cell lymphoma (1 paper, 2020). "Notably, recurrent deletions of COL12A1 have been identified in primary central nervous system lymphoma, and thus we now have identified a second B cell lymphoma with recurrent genetic alterations of this gene." (PMID 32316399, 2020).
cervical cancer (1 paper, 2023). A primary or metastatic malignant neoplasm involving the cervix. "The aberrant expression of many of them were positively correlated with the risk of cervical cancer, with the KM curves of four conveying significance, including COL4A1, COL4A2, COL5A1, and COL12A1, which implied their potential application in clinical diagnosis." (PMID 36683048, 2023).
Cirrhosis (1 paper, 2015). A chronic disorder of the liver in which liver tissue becomes scarred and is partially replaced by regenerative nodules and fibrotic tissue resulting in loss of liver function. "Patients with cirrhosis showed increased expression in blood of eight genes coding for collagen synthesis COL4A6, COL5A1, COL11A2, COL12A1, COL27A1, COL28A1, COL23A1, COL14A1." (PMID 26317806, 2015).
diabetic nephropathy (1 paper, 2017). "COL12A1 is identified as the only collagen gene that up-regulated almost two fold in the db/db diabetic nephropathy mouse model, compared with normal mice." (PMID 27802793, 2017).
diabetic retinopathy (1 paper, 2021). "Upregulation of circ_001209 contributes to vascular dysfunction in diabetic retinas through regulating miR-15b-5p and COL12A1, providing a potential treatment strategy for diabetic retinopathy." (PMID 34233716, 2021). "In conclusion, we have provided strong evidence that the upregulation of circ_001209 leads to retinal vascular dysfunction in diabetic retinopathy through the regulation of miR-15b-5p and COL12A1." (PMID 34233716, 2021).
distal myopathy (1 paper, 2019). Distal myopathy refers to a group of muscle diseases which share the clinical pattern of predominant weakness and atrophy beginning in the feet and/or hands. "This study characterizes a distal myopathy phenotype in adults with dominant COL12A1 pathogenic variants, further defining the phenotypic spectrum and natural history of COL12A1‐related myopathies." (PMID 31509352, 2019).
Ehlers-Danlos syndrome (1 paper, 2021). The Ehlers–Danlos syndromes (EDS) are a clinically and genetically heterogeneous group of heritable connective tissue disorders (HCTDs) characterized by joint hypermobility, skin hyperextensibility, and tissue fragility. "Pathogenic variants in COL12A1, COL6A1, COL1A1, and COL5A1 have been described in individuals with different subtypes of the connective tissue disorders Ehlers-Danlos Syndrome and osteogenesis imperfecta." (PMID 33649486, 2021).
glioblastoma multiforme (1 paper, 2014). "Similarly, COL12A1 was upregulated with the growth of glioblastoma multiforme compared with normal brain, and when the proliferative potential of SKOV3 cells was reduced by knocking down the expression of RUNX1, COL12A1 expression also decreased." (PMID 24780490, 2014).
hepatic (1 paper, 2025). "Differential regulation of the hepatic stellate cell activation and hepatic fibrosis pathways was largely driven by upregulation of 17 collagen isoforms, including COL12A1, COL15A1, COL16A1, and COL1A1." (PMID 40040391, 2025).
hepatocellular carcinoma (1 paper, 2021). A malignant tumor that arises from hepatocytes. "LA14 alleviated the d-GalN-induced upregulation of ROCK2, FBLIM1, and COL12A1, which suggested that LA14 might contribute to the prevention of hepatocellular cancer during acute liver injury." (PMID 34128694, 2021).
Hyperglycemia (1 paper, 2024). An increased concentration of glucose in the blood. "In DR, research has shown that miR-15b-5p inhibits the expression of COL12A1, a gene encoding collagen type XII α 1 chain, and inhibits the proliferation, migration, and angiogenesis of hyperglycemia-induced human retinal vascular endothelial cells." (PMID 38645427, 2024).
Hypertension (1 paper, 2021). The presence of chronic increased pressure in the systemic arterial system. "Importantly, hypertension is a major characteristic of PE, which suggests that COL12A1 may be a potential candidate biomarker for the assessment of PE." (PMID 34697885, 2021).
Insulin resistance (1 paper, 2017). Increased resistance towards insulin, that is, diminished effectiveness of insulin in reducing blood glucose levels. "In AGE-treated animals, insulin resistance, adipose macrophage infiltration and Col12a1 mRNA were increased with no changes in M1 and M2 phenotypes as compared to C-albumin-treated rats." (PMID 29018354, 2017).
joint disorders (1 paper, 2021). "Some partial correlation between COL12A1 Single Nucleotide Polymorphisms (SNPs) and joint disorders was previously reported; however, just one of the studies brought up the relationship between rs970547 in COL12A1 with anterior cruciate ligament (ACL) rupture." (PMID 34062975, 2021).
keloid (1 paper, 2022). An irregularly shaped, elevated mark on the skin caused by deposits of excessive amounts of collagen during wound healing. "In both studies, the accumulation of collagens showed molecule‐specific (e.g., upregulated COL12A1 vs. downregulated COL6A3 in keloids)." (PMID 35435317, 2022).
Kyphoscoliosis (1 paper, 2022). An abnormal curvature of the spine in both a coronal (lateral) and sagittal (back-to-front) plane. "Mice with Col12A1 knockout showed muscle weakness with decreased grip strength, combined with bone fragility, short stature, and kyphoscoliosis." (PMID 35368668, 2022).
meningioma (1 paper, 2020). A generally slow growing tumor attached to the dura mater. "As per the heatmap it is visible that NDRG1, MRC2, and COPS8 is highly abundant in the higher grades of meningiomas whereas more abundances of COL14A, COL12A1 were found in the non-tumor controls." (PMID 32974197, 2020).
mucinous adenocarcinoma (1 paper, 2020). An invasive adenocarcinoma composed of malignant glandular cells which contain intracytoplasmic mucin. "Further analysis showed that COL12A1 alteration rates in different cancer type such as mucinous adenocarcinoma, colon, and rectal adenocarcinoma were successively 25%, 12%, and 10%." (PMID 32356618, 2020). "In our study, 12% of COL12A1 alteration occurred in CRC, and alteration frequency of COL12A1 in mucinous adenocarcinoma of colon and rectum was the highest, which was up to 25%." (PMID 32356618, 2020).
Myocardial fibrosis (1 paper, 2022). "In the heart, Col12a1 usually appears as a marker of myocardial fibrosis." (PMID 35211156, 2022).